IGFBP5 (insulin like growth factor binding protein 5)
Diseases named in the same sentence as IGFBP5 in open-access papers (continued):
Sharing a sentence is not in itself a finding about the gene and the disease.
high blood pressure (1 paper, 2024). "Transcript levels for genes linked to cardiac damage, including hypertrophy (ANP and BNP), cardiac fibrosis (COL I and COL III), and hypertension-related injury (IGFBP5 and RNF207), were determined by qPCR." (PMID 39796124, 2024). "As markers of cardiac injury related to high blood pressure, we also measured insulin-like growth factor binding protein 5 (IGFBP5) and ring finger protein 207 (RNF207) levels that were previously identified through whole transcriptome analysis in the mouse." (PMID 39796124, 2024). "An increase in IGFBP5 and a decrease in RNF207 RNA levels were identified as markers of cardiac injury related to high blood pressure, based on a whole transcriptome analysis in the mouse." (PMID 39796124, 2024).
hyperandrogenism (1 paper, 2025). Excessive secretion of androgens from the adrenal glands or gonads. "The proteins IGFBP5, LAMP2, and CDH5 may contribute to the mechanisms underlying the adverse effects of hyperandrogenism on oocyte quality in PCOS patients." (PMID 40444232, 2025). "In summary, IGFBP5, LAMP2, and CDH5 may be involved in the process by which hyperandrogenism affects oocyte quality in PCOS patients." (PMID 40444232, 2025).
hypothyroidism (1 paper, 2025). Abnormally low levels of thyroid hormone. "With the exception of IGFBP5, all IGFBPs experienced at least one significant downregulation in the LVR as a result of MMI‐induced hypothyroidism." (PMID 40693299, 2025). "Interestingly, however, while IGFBP3 was impacted by fetal hypothyroidism, there was minimal to no impact on expression of the highly related genes IGFBP5 and IGFBP6." (PMID 40693299, 2025).
intraepithelial neoplasia (1 paper, 2009). A precancerous neoplastic process that affects the squamous, glandular, or transitional cell epithelium without evidence of invasion. "We presume that in intraepithelial neoplasia, the body compensatorily up-regulates the expression of IGFBP-5, which activates the caspase-8 signal transduction pathway, increases the structure sensitivity to TNF-α, induces the internal apoptosis pathway, and delays tumor advancement." (PMID 19476635, 2009).
liposarcoma (1 paper, 2017). A usually painless malignant tumor that arises from adipose tissue. "The up-regulation of IGFBP5 mRNA and protein upon treatment with selinexor was further verified both at the mRNA and protein levels in liposarcoma cell lines." (PMID 27893412, 2017). "Our microarray data analysis showed that IGFBP5 expression was markedly increased in liposarcoma cells after treatment with selinexor." (PMID 27893412, 2017). "Further, overexpression and knockdown experiments showed that IGFBP5 acts as a tumor suppressor and its expression was restored upon selinexor treatment of liposarcoma cells." (PMID 27893412, 2017). "Many previous reports showed that IGFBP5 can act either as a tumor suppressor or oncogene in a tissue-specific context but nothing is known about the role of IGFBP5 in human liposarcoma." (PMID 27893412, 2017). "We provide evidence that IGFBP5 can acts as a tumor suppressor in liposarcoma cells in an IGF-1 dependent manner; and selinexor can markedly up-regulate the expression of this tumor suppressor protein." (PMID 27893412, 2017). "RNA-sequencing analysis confirmed down-regulation of IGFBP5 mRNA in liposarcoma cell lines compared to human adipose tissue (manuscript in preparation)." (PMID 27893412, 2017). "Notably, we found that selinexor increased expression of IGFBP5 both at the mRNA and protein levels in liposarcoma cells." (PMID 27893412, 2017). "Overall, our study showed that selinexor treatment restored tumor suppressive function of IGFBP5 and inhibited aurora kinase A and B in liposarcoma cells supporting the usefulness of selinexor as a potential therapeutic strategy for the treatment of this cancer." (PMID 27893412, 2017).
lymphedema (1 paper, 2025). Excess fluid collection in tissues, causing swelling. "Igfbp5 was of particular interest because it was the most profoundly down-regulated gene in the lymphedema model; the Igfbp5 mRNA levels were reduced by 55%, consistent with quantitative reverse-transcription PCR (RT-qPCR) analysis, which showed a decrease of 46%." (PMID 40060910, 2025).
macrosomia (1 paper, 2025). "IGFBP-2 and IGFBP-5 emerged as significant independent predictors of LGA birth in adjusted models (OR = 2.515 and 2.402, respectively; p < 0.001), consistent with prior studies linking first-trimester IGF-1 and IGF-1/IGFBP-1 ratios to macrosomia." (PMID 40943286, 2025).
metastatic cancer (1 paper, 2014). A carcinoma which has spread from the original site of growth to another anatomic site. "Vitronectin and IGFBP-5 immunoreactivity was lower while β1 integrin immunoreactivity was higher in the stroma surrounding metastatic cancer tissues, as compared to normal breast and primary cancer stromal tissues." (PMID 25167778, 2014).
metastatic prostate carcinoma (1 paper, 2017). A carcinoma that arises from the prostate gland and has spread to other anatomic sites. "The structurally similar protein IGFBP5 has also been found to be downregulated in metastatic prostate cancer." (PMID 27966447, 2017).
non-small cell lung carcinoma (1 paper, 2025). A group of at least three distinct histological types of lung cancer, including non-small cell squamous cell carcinoma, adenocarcinoma, and large cell carcinoma. "Additionally, low serum IGFBP5 levels have been proven to correlate strongly with a positive nodal status, which provides diagnostic value for identifying non-small cell lung cancer progression and patient outcome." (PMID 40672360, 2025).
pancreatic ductal adenocarcinoma (1 paper, 2022). An infiltrating adenocarcinoma that arises from the epithelial cells of the pancreas. "IGFBP5 protein expression is elevated in pancreatic ductal adenocarcinoma (PDAC) tissue and is strongest at the leading edge of the tumor, when compared to IHC staining of non-malignant duct specimens." (PMID 36465383, 2022). "IGFBP5 is upregulated in pancreatic ductal adenocarcinoma and expression is increased in the islet cells closest to the periphery of the tumor." (PMID 36465383, 2022).
peripheral nerve injury (1 paper, 2022). Injury to a peripheral nerve. "In addition, it was well known that IGFBP5 not only induces cell differentiation but may also modulate the hypersensitivity of nociceptive neurons in a peripheral nerve injury mouse model." (PMID 36532077, 2022).
psoriasis (1 paper, 2023). An autoimmune condition characterized by red, well-delineated plaques with silvery scales that are usually on the extensor surfaces and scalp. "Therefore, the role of IGFBP5 in psoriasis may be controversial and requires further investigation." (PMID 37816883, 2023).
rectal cancer (1 paper, 2019). A primary or metastatic malignant neoplasm that affects the rectum. "In addition to SMAD7 (P = 0.0005) and SMAD3 (P = 0.0003), several other genes or genetic regions (CYP2R1, CHAF1A, CREBBP, IL10, SNPs identified in genome-wide association studies (GWAS) to be associated with IGF levels, IGFBP2/IGFBP5, IGFBP3, and C-MYC region) were associated with rectal cancer." (PMID 31434255, 2019).
spinocerebellar ataxia (1 paper, 2014). "For instance, two spinocerebellar ataxia (SCA) mouse models (for SCA1 and SCA7) showed a down-regulation of insulin-like growth factor binding protein 5 (Igfbp5) transcripts." (PMID 26331037, 2014).
tauopathy (1 paper, 2024). Neurodegenerative disorders involving deposition of abnormal tau protein isoforms (tau proteins) in neurons and glial cells in the brain. "This could contribute to neurodegeneration through oxidative stress, Aβ toxicity, and tauopathy, and IGFBP-5 may influence AD pathology via direct interactions with Aβ." (PMID 39448576, 2024).
thyroid tumour (1 paper, 2021). "These two SNPs were highly correlated to rs57481445 (r2 > 0.9) and also strongly associated with the expression of DIRC3 and IGFBP5 (insulin growth factor binding protein 5) in thyroid tumour cells, according to TCGA data." (PMID 33747362, 2021). "It is also associated with expression of DIRC3 and of the nearby gene IGFBP5 in thyroid tumour cells." (PMID 33747362, 2021). "This SNP was strongly associated with the expression of the two nearby genes DIRC3 and IGFBP5 in thyroid tumour cells, according to TCGA data." (PMID 33747362, 2021). "Since it was shown that IGFBP5 is overexpressed in PTC, it could have a proliferative effect on thyroid tumour cells." (PMID 33747362, 2021).
triple-negative breast carcinoma (1 paper, 2022). An invasive breast carcinoma which is negative for expression of estrogen receptor (ER), progesterone receptor (PR), and human epidermal growth factor receptor 2 (HER2).
type I diabetes (1 paper, 2015). "Furthermore, elevated protein levels of IGFBP5 and reduced protein levels of IGF1 are found in young patients with type I diabetes showing decreased bone mass." (PMID 26025657, 2015).
ZIKV infection (1 paper, 2022). "ZIKV infection alone was also able to reduce IGFBP5 expression in U251 cells at 48 hpi." (PMID 36680137, 2022).
tumor (143 papers, 2005 to 2026). "Altogether, this data suggests plausible mechanisms of actions that can explain why IGFBP5 levels associated with lower tumor stage and favorable survival in the two analyzed patient cohorts." (PMID 40234830, 2025). "Additional analyses of IGFBP5 expression in both the discovery cohort and the validation cohort revealed an association with lower tumor stage." (PMID 40234830, 2025). "DIRC3 and IGFBP5 (insulin-like growth factor binding protein 5) tumor suppressors are within the same topologically associated domain." (PMID 33218058, 2020). "Using immunohistochemistry, these authors showed that IGFBP5 overexpression was significantly associated with advanced tumor stage, and that it was an independent predictor of poor disease-specific survival and metastasis-free survival." (PMID 28882129, 2017). "In another example, the risk allele (A) of rs6721996 increased the susceptibility of IGFBP5 transcription to aberrant FOXA1 expression in tumor." (PMID 26001967, 2015). "Moreover, IGFBP5 expression was associated with tumor infiltration of B cells, T cells, macrophages, and NK cells." (PMID 38164271, 2024). "Some research has shown that IGFBP5 was implicated in numerous malignancies as an oncogene 8, while other studies have shown that IGFBP5 could restrain tumor growth and metastasis." (PMID 38164271, 2024). "Senescent fibroblasts can acquire a senescence-associated secretory phenotype which can promote tumor progression indicating that IGFBP5 may be involved in the generation of CAFs." (PMID 36093095, 2022). "Furthermore, after TMEM16A blockade, the expression profiles of explants showed strong upregulation of IGFBP5 (a potent antiangiogenic factor associated with tumor suppression)." (PMID 33681289, 2021). "Furthermore, a tumour-specific pathway is implicated, with negligible levels of IGFBP-5 and IGFBP-2 in normal breast epithelial cells[B6,39,40]." (PMID 15642160, 2005). "A potential tumor-suppressive mechanism is suggested by a study in which circulating miR-193b was shown to be downregulated in gestational diabetes patients compared to healthy controls, associated with increased apoptosis and autophagy through an increase in IGFBP-5." (PMID 35597813, 2022). "Collectively, our findings highlight IGFBP-5 as a potential prognostic marker, demonstrate the tumour-inhibitory effect of ERβ silencing, and identify GPER1 as a promising therapeutic target linking estrogen signalling, lipid metabolism, and CRC progression." (PMID 42047268, 2026). "IGFBP5 is induced by tumor growth-suppressive mesenchymal stromal cells and dampens RMS cell proliferation." (PMID 40234830, 2025). "The data further supports that IGFBP5 provides anti-tumor growth signals involving growth arrest and apoptosis." (PMID 40234830, 2025). "This study uses functional modeling and omics approaches to identify IGFBP5 as a candidate mediator of anti-tumor growth mechanisms originating from tumor-neighboring mesenchymal stromal cells." (PMID 40234830, 2025). "The authors identified 245 candidate lncRNAs associated with melanoma whose loci are jointly bound by MITF and SOX10, suggesting that DIRC3 exerts broad tumour-suppressive effects through IGFBP5-dependent mechanisms." (PMID 41463281, 2025). "Our present study uses diverse sets of model systems and patient material to demonstrate that mesenchymal stromal cells nourish high IGFBP5 levels in the tumor microenvironment and promote myogenic identity of RMS cells." (PMID 40234830, 2025). "Single cell RNA sequencing data was next explored to characterize the expression pattern of IGFBP5 across different cell types in the human RMS tumor microenvironment." (PMID 40234830, 2025).
tumor (continued). "Following cell preparation, ClariomD gene expression analysis identified IGFBP5 as the most significantly upregulated gene in RMS cells exposed to the naïve mesenchymal stromal cells with tumor growth-suppressive activity." (PMID 40234830, 2025). "Especially ECM composition of representative tumor microenvironments with local enrichment of IGFBP5 is difficult to model correctly." (PMID 40234830, 2025). "Specifically, this network suppresses DIRC3 transcription, which in turn regulates chromatin accessibility to limit SOX10 and maintain expression of tumour-suppressive genes such as IGFBP5." (PMID 41463281, 2025). "In brief, IGFBP-1, IGFBP-2, IGFBP-3, and IGFBP-5 have been shown to elevate PD-L1 expression on macrophages and tumor cells, leading to reduced immune response in gliomas, esophageal, and colorectal cancers." (PMID 41226289, 2025). "DIRC3 acts in the nucleus and has been shown to activate expression of the neighbouring insulin-like growth factor binding protein 5 (IGFBP5) gene, which shapes tumour suppression by modulating the insulin-like growth factor 1 receptor (IGF1R) pathway." (PMID 41463281, 2025). "From the Clariom D-based gene expression analysis, IGFBP5 was identified as the major upregulated gene in RMS cells exposed to tumor growth-suppressive stromal cells." (PMID 40234830, 2025). "We study the role of IGFBP5 in some cell biological processes that mediate the tumor growth and metastasis process." (PMID 38896333, 2024). "Vascular invasion within the tumor and high expression of CUB domain-containing protein (CDCP1) and low levels of insulin-like growth factor binding protein (IGFBP5 and IGFBP7) in the bloodstream have been reported as risk factors for lymph node recurrence." (PMID 38472943, 2024). "IHC analysis of tumour tissues showed lower levels of IGFBP5 and Ki67 proteins in circJUN‐silenced tumours, while tumours from circJUN‐overexpressing tumours showed increased protein levels of both IGFBP5 and Ki67." (PMID 39307884, 2024). "When we examined all the cell populations in our dataset, we confirmed minimal IGFBP3 expression in RCC tumor cells as well as IGFBP5 expression in pericytes, which have an overlapping gene expression signature with arterial smooth muscle cells." (PMID 39516665, 2024). "For instance, in bladder cancer, transcriptomic analysis of 200 patients and five normal samples revealed IGFBP-5 as a tumor sensitivity predictor of anti-IGF therapy that inversely corelated with IGF phosphorylation pathways." (PMID 38395880, 2024). "As a potential tumor suppressor, IGFBP5 is capable of restraining tumor growth and progression via regulating the MAPK/ERK and PI3K/AKT signaling." (PMID 39164746, 2024). "In the orthotopic mouse model, ectopic IGFBP5 overexpression substantially increased the non-invasive 83 GSC tumor volume and significantly reduced the mice survival." (PMID 36949068, 2023). "Tumor tissues mainly contain cytoplasmic IGFBP5, whereas cell lines with exogenously introduced IGFBP5 include mainly nuclear IGFBP5 acting as a growth inhibitor." (PMID 37620794, 2023). "IGFBP5, a marker of tumor-derived clusters 6 and 16, was further examined in tissue sections by immunofluorescence, and the result confirmed presence of these clusters as separate cellular entities." (PMID 37644609, 2023). "Circulating tumor cells (CTCs) are enriched for IGFBP5 and the IGFBP5 expressing CTCs are localized to the epithelial-stromal boundary." (PMID 36465383, 2022).